ENSG00000257341 (novel protein)
Gene: Protein-coding gene on chromosome 14 (105,487,199 to 105,492,267, forward strand). Ensembl gene ENSG00000257341.
Genetic constraint (gnomAD): Missense variants: 122 observed, 102.16 expected, observed/expected ratio (o/e) 1.19, 90% interval 1.03 to 1.39. Synonymous variants: 41 observed, 37.73 expected, observed/expected ratio (o/e) 1.09, 90% interval 0.85 to 1.41.